PTX3 (pentraxin 3)
Diseases named in the same sentence as PTX3 in open-access papers (continued):
Sharing a sentence is not in itself a finding about the gene and the disease.
leiomyosarcoma (3 papers, 2016 to 2022). An uncommon, aggressive malignant smooth muscle neoplasm, usually occurring in post-menopausal women. "Hypermethylation of the promoter region and of an enhancer encompassing the second PTX3 exon (enhancer 2) have been associated with PTX3 gene silencing in selected human tumors (e.g., colon rectal cancer and leiomyosarcoma)." (PMID 31019517, 2019). "PTX3 expression was epigenetically regulated in selected human tumors (e.g., leiomyosarcomas, SKCM, and CRC) by methylation of the promoter region and of a putative enhancer." (PMID 36139597, 2022).
leprosy (3 papers, 2020 to 2023). Leprosy is a chronic infectious disease affecting primarily the skin and peripheral nervous system. "The aim of this study was to evaluate the association of PTX3 gene polymorphisms and PTX3 plasma levels with susceptibility to leprosy and clinical characteristics." (PMID 38053036, 2023). "In the present study, we investigated for the first time the association of rs1840680 and rs2305619 polymorphisms in PTX3 and PTX3 plasma levels with leprosy susceptibility and clinical characteristics." (PMID 38053036, 2023). "In summary, our results demonstrated that PTX3 levels are elevated in leprosy patients when compared to healthy household contacts or blood donors, and that PTX3 levels decrease after initiation of MDT." (PMID 38053036, 2023). "On the other hand, this is the first study in the literature to determine the frequency of PTX3 polymorphisms in leprosy patients and to demonstrate the influence of MDT on PTX3 levels." (PMID 38053036, 2023). "In the present study, we demonstrated that individuals with leprosy have higher levels of PTX3 than healthy individuals, including household contacts without clinical manifestations or blood donors." (PMID 38053036, 2023). "On the other hand, plasma levels of PTX3 were significantly higher in patients with leprosy when compared to household contacts (p = 0.003) or blood donors (p = 0.04)." (PMID 38053036, 2023). "For the measurement of plasma levels of PTX3, 142 leprosy patients, 52 household contacts, and 84 blood donors were included." (PMID 38053036, 2023). "Our results suggest that PTX3 may play an important role in the pathogenesis of leprosy and point to the potential use of this molecule as an infection marker." (PMID 38053036, 2023). "In addition, the neutrophil granule protein pentraxin-3 (PTX-3) was found to be increased in the blood of multibacillary leprosy patients, in particular, levels were higher in those that went on to develop ENL." (PMID 35003097, 2021). "In addition, they found that PTX3 serum levels were approximately 1.8 and 2.5 times higher in patients with type 2 reactions than in those with type 1 reactions and multibacillary or paucibacillary leprosy, respectively." (PMID 38053036, 2023). "Therefore, considering that PTX3 is an important acute phase protein involved in the regulation of the complement system, it is likely that PTX3 may play an important role in modulating the immune response in leprosy." (PMID 38053036, 2023). "In this study, we did not observe any significant difference between PTX3 levels and the occurrence of leprosy reaction." (PMID 38053036, 2023). "To assess the relationship of PTX3 levels with the occurrence of leprosy reaction, we included post-MDT leprosy patients who did not develop reaction or who developed type 1 or type 2 reactions." (PMID 38053036, 2023).
leptospirosis (3 papers, 2013 to 2025). A contagious bacterial infection caused by spirochetes of the genus Leptospira. "Previously, the association between long pentraxin PTX3, the protein that is in the same class as C-reactive protein, and mortality in severe leptospirosis was reported, where the serum PTX3 and IL-6 levels were higher in non-survivors." (PMID 33175842, 2020).
liver cancer (3 papers, 2020 to 2025). An epithelial or non-epithelial malignant neoplasm that arises from the liver. "This study aimed to examine serum pentraxin 3 levels in patients with primary liver cancer and to assess its potential as a diagnostic and prognostic biomarker." (PMID 39686456, 2024). "First, this is the first study to evaluate the potential of serum PTX3 as a biomarker for both the diagnosis and prognosis of primary liver cancer, potentially advancing diagnostic and treatment strategies." (PMID 39686456, 2024). "Serum PTX3 levels are elevated in liver cancer patients and high serum PTX3 levels are associated with poor prognosis." (PMID 39686456, 2024). "Serum PTX3 levels are elevated in patients with primary liver cancer and high serum PTX3 levels are associated with poor prognosis." (PMID 39686456, 2024). "This study presents a comprehensive analysis of serum PTX3 levels in patients with primary liver cancer and evaluates its diagnostic and prognostic significance." (PMID 39686456, 2024). "By examining the association between serum PTX3 levels and clinical outcomes in patients with primary liver cancer, we hope to explore its potential utility in clinical practice." (PMID 39686456, 2024). "The diagnostic performance of PTX3 was assessed using ROC curve analysis and compared with the liver cancer tumor markers AFP and CA199." (PMID 39686456, 2024). "On the other hand, PTX3 promotes cancer initiation and metastasis in certain cancers, including liver cancer." (PMID 41479916, 2025). "Serum PTX3 levels were elevated in patients with primary liver cancer compared to those in healthy control subjects." (PMID 39686456, 2024). "This suggests that serum PTX3 has the potential to be a valuable biomarker for predicting liver cancer recurrence." (PMID 39686456, 2024). "PTX3 was able to differentiate liver cancer patients from healthy control subjects with an AUC of 0.734, a sensitivity of 73.24%, and a specificity of 84.78% (95% CI: 0.531–0.892)." (PMID 39686456, 2024). "The prognostic significance of serum PTX3 in patients with primary liver cancer was assessed using Kaplan–Meier survival curves." (PMID 39686456, 2024). "First, we did not explore the specific mechanisms responsible for elevated serum PTX3 levels in liver cancer patients." (PMID 39686456, 2024). "The study also investigated the correlation between PTX3 levels and the clinicopathological characteristics of patients with primary liver cancer." (PMID 39686456, 2024). "This study aimed to investigate the potential of serum PTX3 as a biomarker for the diagnosis and prognosis of primary liver cancer." (PMID 39686456, 2024). "Correlations of serum PTX3 levels with clinicopathological characteristics of liver cancer patients." (PMID 39686456, 2024). "With a cut-off value of 5.1 ng/mL, PTX3 effectively differentiated patients with primary liver cancer from healthy control subjects, achieving an AUC of 0.734, a sensitivity of 73.24%, and a specificity of 84.78%." (PMID 39686456, 2024). "The effectiveness of serum PTX3 in diagnosing primary liver cancer was evaluated using receiver operating characteristic (ROC) curves and their corresponding areas under the curve (AUC)." (PMID 39686456, 2024). "This suggests that serum PTX3 has the potential to be a novel biomarker for both the diagnosis and prognosis of primary liver cancer." (PMID 39686456, 2024). "This study revealed that serum PTX3 levels were elevated in patients with liver cancer compared to the healthy controls." (PMID 39686456, 2024). "This suggests that serum PTX3 has potential as a novel biomarker for both the diagnosis and prognosis of liver cancer." (PMID 39686456, 2024). "Additionally, liver cancer patients with higher serum PTX3 levels exhibited lower overall survival and RFS rates compared to those with lower levels." (PMID 39686456, 2024).
liver cancer (continued). "To determine whether serum PTX3 originated from liver cancer tumor tissues, we measured serum PTX3 concentrations before and after the surgical removal of liver cancer tumors." (PMID 39686456, 2024). "Patients with liver cancer were divided into 2 groups based on the median serum PTX3 levels." (PMID 39686456, 2024). "Future studies should focus on determining the timeframe needed for postoperative serum PTX3 levels to return to normal, as this could provide important information for monitoring liver cancer recurrence." (PMID 39686456, 2024). "However, further multi-center clinical studies are needed to validate the use of serum PTX3 as a reliable biomarker for the diagnosis and prognosis of primary liver cancer and to explore the specific mechanisms responsible for the increased serum PTX3 levels in liver cancer patients." (PMID 39686456, 2024). "Furthermore, the levels of PTX3, AFP, and CA199 were significantly elevated in the liver cancer group compared to the healthy control group (P < .05)." (PMID 39686456, 2024). "Of note, serum PTX3 did not increase with the TNM stages in liver cancer." (PMID 32078718, 2020).
liver cirrhosis (3 papers, 2020 to 2024). "In the present study, PTX3 protein was determined in systemic, hepatic, and portal vein plasma of patients with liver cirrhosis to assess a possible association between hepatic PTX3 release and extent of liver injury." (PMID 32078718, 2020). "This suggests that raised PTX3 in liver cirrhosis may in part compensate for deficiencies in pro- as well as anticoagulatory pathways." (PMID 32078718, 2020). "Though circulating PTX3 in patients with liver cirrhosis was supposed as a marker of immune cell activation, high levels are also attributed to diminished hepatic excretion." (PMID 32078718, 2020). "Moreover, we postulated positive correlations of hepatic vein PTX3 with measures of liver function in patients with liver cirrhosis and patients with HCC." (PMID 32078718, 2020). "PTX3 was similar in patients with compensated and decompensated liver cirrhosis." (PMID 32078718, 2020). "Liver cirrhosis is a risk factor for HCC, and PTX3 may also have a role herein." (PMID 32078718, 2020). "Impaired hepatic removal of PTX3 in liver cirrhosis may contribute to increased plasma levels." (PMID 32078718, 2020). "Pentraxin 3 is an adequate indicator of inflammation in patients with liver cirrhosis but was not related to PCSK9 levels in any of the blood compartments." (PMID 33461570, 2021). "This excludes PTX3 as a marker of residual hepatic function and common complications of liver cirrhosis." (PMID 32078718, 2020). "Anyhow, circulating PTX3 is not of prognostic value in liver cirrhosis or HCC." (PMID 32078718, 2020).
lymph node metastasis (3 papers, 2021 to 2024). "It was suggested that oral cancer patients with PTX3 genetic variant rs3816527 in smoking were linked to the development of late-stage cancer and the increase of lymph node metastasis." (PMID 33967610, 2021).
lymphoma (3 papers, 2023 to 2025). A malignant (clonal) proliferation of B- lymphocytes or T- lymphocytes which involves the lymph nodes, bone marrow and/or extranodal sites. "The findings highlight PTX3 as a potential treatment in lymphoma." (PMID 40426926, 2025).
malaria (3 papers, 2016 to 2025). Malaria is a serious and sometimes fatal disease caused by a parasite that commonly infects a certain type of mosquito which feeds on humans. "Cross-sectional malaria studies report higher PTX3 concentrations in severe or cerebral disease compared with milder forms, consistent with PTX3 as a marker of inflammatory activation in parasitic infections." (PMID 41471254, 2025). "Our findings showed the potential of four soluble receptors including sEPCR, sICAM-1, suPAR and sTie-2 with its ligand Ang-2, and two other molecules PCT, and PTX3, as informative biomarkers of malaria disease severity, coma and mortality." (PMID 35204613, 2022).
metastatic disease (3 papers, 2019 to 2024). "A one-unit increase in PTX3 levels was associated with 1.27 times higher odds of developing metastatic disease; however, this was not statistically significant (OR: 1.27, 95% CI: 0.97–1.65)." (PMID 38542446, 2024). "However, high PTX3 levels were associated with a more aggressive disease, as indicated by tumour stage and the development of metastatic disease, and thus circulating PTX3 levels could be a potential biomarker for prognostication of BC." (PMID 38542446, 2024). "Patients who developed metastatic disease during follow-up (n = 16) had significantly higher PTX3 plasma levels at baseline compared to patients without metastatic progression during follow-up (p = 0.009)." (PMID 38542446, 2024). "However, the potential value of PTX3 as a prognostic biomarker was indicated by significantly higher PTX3 levels in patients who developed metastatic disease during follow-up compared to patients who did not develop metastatic disease." (PMID 38542446, 2024).
Neonatal sepsis (3 papers, 2020 to 2024). Systemic inflammatory response to infection in newborn babies. "Although this study may have some limitations, for the diagnosis of neonatal sepsis, the sensitivity of biomarkers is more important than the specificity, so PTX-3 seems to be superior to CRP as a diagnostic biomarker for neonatal sepsis." (PMID 39021820, 2024). "In conclusion, pentraxin 3 seems like a promising prognostic marker in neonatal sepsis." (PMID 35449688, 2022).
nephritis (3 papers, 2019 to 2024). Inflammation of renal tissue. "Research revealed significantly elevated levels of serum pentraxin-3 (PTX3) in patients with active LN, showing a significant relationship between PTX3 levels and renal pathology index scores, particularly interstitial inflammation in active nephritis." (PMID 39104393, 2024).
ovarian hyperstimulation syndrome (3 papers, 2020 to 2024). A complication of ovulation induction in infertility treatment. "Recently, researchers from Helsinki found that circulating PTX3 levels during in vitro fertilization could provide benefits in risk assessment for ovarian hyperstimulation syndrome." (PMID 34856980, 2021). "We evaluated the value of PTX3 in the prediction of ovarian hyperstimulation syndrome (OHSS), a severe complication of in vitro fertilization (IVF)." (PMID 32372340, 2020).
papilloma (3 papers, 2015 to 2019). A benign epithelial neoplasm that projects above the surrounding epithelial surface and consists of villous or arborescent outgrowths of fibrovascular stroma. "Accordingly, invasive bladder cancer HT1376 cell xenografts grew faster and expressed negligible levels of PTX3 following in vivo implantation in immune-compromised mice when compared to lower grade 5637 lesions and papilloma-derived RT4 grafts." (PMID 31480336, 2019).
peripheral arterial disease (3 papers, 2013 to 2024). A disorder of the arteries supplying the upper and lower extremity and the visceral organs. "These animal experiments are supported by a recent study showing that circulating endothelial progenitor cells (which promote vascular repair and vasculogenesis) correlate with PTX3 in patients with peripheral artery disease." (PMID 23658833, 2013). "A literature review demonstrated the association of the presence of elevated PTX-3 values with the severity of peripheral arterial disease but did not specifically discuss critical ischemia." (PMID 38672153, 2024).
respiratory failure (3 papers, 2023 to 2024). The significant impairment of gas exchange within the lungs resulting in hypoxia, hypercarbia, or both, to the extent that organ tissue perfusion is severely compromised. "Serum PTX3 concentrations were significantly higher in patients admitted to the PICU, patients with respiratory failure, VAP, and patients who required mechanical ventilation in management." (PMID 39294659, 2024). "By demonstrating a positive correlation with the peak temperature, length of hospital stays, PRESS score, respiratory failure, need for mechanical ventilation, and PICU admission, we found out that the level of PTX3 represents the severity of the disease in children with LRTI." (PMID 39294659, 2024).
respiratory infection (3 papers, 2021 to 2023). "Previous work demonstrated the protective effects of PTX3 against respiratory infection with Klebsiella pneumoniae in transgenic mice that overexpress PTX3." (PMID 33925033, 2021). "A similar observation has also been demonstrated in Klebsiella pneumoniae: the overexpression of PTX3 in mice given a low dose of bacteria promoted resistance to K. pneumoniae respiratory infection, while in mice given a high inoculum, overexpression of PTX3 was associated with faster lethality." (PMID 36977278, 2023).